ACAN (aggrecan)
Diseases named in the same sentence as ACAN in open-access papers (continued):
Sharing a sentence is not in itself a finding about the gene and the disease.
osteoarthritis (continued). "Its levels in synovial fluid were significantly associated with the degradation markers of aggrecan, AGG1 and AGG2, suggesting that adiponectin may also be involved in the regulation of cartilage matrix degradation during the progression of osteoarthritis." (PMID 39409194, 2024). "Additionally, increased aggrecan fragments have been observed in patients with RA and osteoarthritis (OA), suggesting that these patients have altered aggrecan profile." (PMID 39768826, 2024). "Finally, proteoglycans, in particular aggrecan, mimicking polymers have shown satisfactory results in osteoarthritis clinical applications." (PMID 36342580, 2023). "Synovial fluid from osteoarthritis (OA, n ​= ​25) and knee-injury (n ​= ​13) patients, a synovial fluid pool (SF-control) and purified aggrecan, were chondroitinase digested and together with CS- and HA-standards fluorophore labelled prior to quantitative HPLC analysis." (PMID 37426292, 2023). "In order to establish an animal model of chondrocyte senescence, we found that with the increase of age, the articular cartilage gradually became degenerated and displayed osteoarthritis features with the decreased expression of chondrocyte anabolic marker AGGRECAN." (PMID 37217512, 2023). "Agents that prevent aggrecan degradation and restore its production might be critical for the treatment of early-onset osteoarthritis." (PMID 35205249, 2022). "Increased aggrecan degradation is a key factor in the pathogenesis of osteoarthritis." (PMID 36362216, 2022). "Osteoarthritis (OA), the most common joint disease in the elderly, is characterized by progressive degradation of articular cartilage extracellular matrix, which comprises mainly of the hyaluronan (HA)-aggrecan network and the collagen fibrils." (PMID 36241903, 2022). "Analysis of Pcsk6 KO mice substantiates a role of PCSK6 in aggrecan degradation and osteoarthritis." (PMID 36362216, 2022). "In turn, increased production of COX-2 and prostaglandin E2 by chondrocytes enhances the degradation of both aggrecan (cartilage-specific protein, critical for cartilage structure and the function of joints) and collagen type II in patients with osteoarthritis." (PMID 35270791, 2022). "In osteoarthritis, it is activated by hyaluronan and aggrecan fragments leading to the activation of nuclear factor kappa-light-chain-enhancer of activated B cells (NF-κB) signaling, which may contribute to OA progression and pain." (PMID 34502384, 2021). "Heterozygous mutations in the ACAN gene have been reported in individuals with short stature and advanced bone age, with or without early-onset osteoarthritis and/or osteochondritis dissecans." (PMID 33298914, 2020). "IL‐1β is one of the most important proinflammatory cytokines involved in the pathophysiology of osteoarthritis because it inhibits the synthesis of key components of cartilage—type II collagen and cartilage aggrecan—leading to increased cartilage degradation and aggravated inflammation." (PMID 33304230, 2020). "Aggrecanase-2 (ADAMTS5) gene is responsible for aggrecan degradation that may contribute to cartilage destruction in a mouse osteoarthritis (OA) model." (PMID 30652828, 2019). "It has been reported that interleukin-1 beta (IL-1β), one of the main cytokines involved in the pathogenesis of osteoarthritis, can inhibit cell proliferation, reduce the synthesis of aggrecan and type II collagen, and increase the expression of MMP-13 in chondrocytes." (PMID 29483929, 2018). "In the present study, we investigated the role of IL-6 in osteoarthritis (OA) patients and the effects of the stilbenoids monomethyl pinosylvin and pinosylvin on the expression of the cartilage matrix components aggrecan and collagen II and the inflammatory cytokine IL-6 in human OA chondrocytes." (PMID 30597965, 2018). "Proteolytic cleavage of aggrecan is an important feature in osteoarthritis (OA)." (PMID 28679445, 2017).
osteoarthritis (continued). "Aggrecan degradation is a significant and critical event in early-stage osteoarthritis." (PMID 29137610, 2017). "During the early stages of osteoarthritis it may be possible to retard the destructive process by enhancing the production of aggrecan and inhibiting its degradation." (PMID 26914753, 2014). "CS is one of the major components of articular cartilage, and Csgalnact1-null mice exhibit some osteoarthritis-like changes in cartilage, such as a decreased level of aggrecan and link protein 1, a rapid catabolism of aggrecan, and abnormally aggregated and disarranged type-II collagen fibers." (PMID 22952769, 2012). "In addition, mutations in the aggrecan coding genes, such as ACAN or AGC1, are responsible for Spondyloepimetaphyseal dysplasia (SEMD), osteochondritis dissecans with early and severe onset of osteoarthritis in humans, and a variety of short-stature syndromes with rapid bone maturation." (PMID 35466193, 2022). "Alteration of the osteoarthritis pathway due to RARγ agonist treatment was associated with the up-regulation of catabolic genes (ADAMTS5, HES1, and MMP13), inhibition of cartilage matrix anabolic genes (COL2A1, ACAN, and SOX9) and the up-regulation of death genes (CASP4)." (PMID 32294904, 2020). "This is owing to the effects of enzymes typical of osteoarthritis, such as aggrecanases and matrix metalloproteinases (MMPs), which are elevated and degrade ECM components, including aggrecan." (PMID 40283379, 2025). "Our findings indicate that Pioglitazone mitigates chondrocyte inflammation and osteoarthritis in murine models by inhibiting the expression of inflammatory mediators such as TNF‐α, IL‐6 and PGE2, and by preventing the degradation of aggrecan and collagen II." (PMID 40008494, 2025). "The analysis revealed a notable upregulation of key osteoarthritis markers, such as COL10A1, MMP13, and SPP1, along with downregulating chondrogenic markers, including ACAN, COL1A2, COL2A1, and SOX9." (PMID 39337501, 2024). "In osteoarthritis (OA), articular homeostasis is regulated by microRNA-140 that inhibits ADAMTS-5, an enzyme that cleaves aggrecan and stimulates the synthesis of other inflammatory mediators." (PMID 39170063, 2024). "Decreases in aggrecan and collagen II result in the compression or calcification of the ECM, followed by the acceleration of arthrosis." (PMID 36722313, 2023). "In our study, we observed an increase in MMPs, which was accompanied by a decrease in the mRNA expression levels of key components including aggrecan, collagen, and TIMPs, within the cartilage tissue of rats with MIA-induced osteoarthritis." (PMID 38132929, 2023). "In this research, we attested that CEP showed its protective effects on osteoarthritis by inhibiting catabolism (MMPs and ADAMTS) and enhancing anabolism (aggrecan and collagen II) in vitro and in vivo." (PMID 35800437, 2022). "During osteoarthritis progression, production of ECM components is substantially altered, including collagen I, collagen II, aggrecan, and Runx‐2, which changes the microenvironment of the cartilage and disrupts its integrity." (PMID 34078001, 2021). "In fact, in osteoarthritis, CGRP was also reported to inhibit the gene expression of aggrecan and type II collagen." (PMID 34987701, 2021). "In conclusion, electroacupuncture for osteoarthritis is accomplished by upregulating the expression of HIF-1α, Sox9, and ACAN and downregulating the expression of MMP13 and ADAMTS5." (PMID 34760015, 2021). "The ectopic expression of GAS5 in human osteoarthritis chondrocytes elevates MMP-3 expression and reduces the contents of Collagen II and aggrecan." (PMID 34413821, 2021). "This prominent microRNA can target osteoarthritis (OA)-related mRNAs, ADAMTS-5, MMP13, COl2a1, and ACAN in human articular chondrocytes." (PMID 31847882, 2019).
osteoarthritis (continued). "The levels of collagen II, aggrecan, and MMP-13 in chondrocytes have been found to be dysregulated in degenerative joint diseases including OA, and these abnormal expression patterns can therefore be regarded as biomarkers of chondrocyte function." (PMID 30949498, 2019). "Knockdown of miR-448 significantly increased the expressions of matrilin-3, aggrecan and type II collagen, and decreased the expression of MMP-13 compared with osteoarthritis chondrocytes transfected with anti-miR-NC." (PMID 29483929, 2018). "The specific degradation of type II collagen and aggrecan by matrix metalloproteinase (MMP)-9, -13 and ADAMTS-4 and -5 (aggrecanase-1 and -2) in the cartilage matrix is a critical step in pathology of osteoarthritis (OA)." (PMID 25909781, 2015). "Aggrecan serves as a validated biomarker of cartilage anabolic activity in clinical PTOA assessment, while CTX-II represents an established serum and synovial fluid biomarker for monitoring type II collagen degradation in osteoarthritis patients." (PMID 41323462, 2025). "After histological staining of mouse knee joint sections, we further confirmed a significant reduction in IRS2 protein levels in DMM-induced osteoarthritis (OA), accompanied by an increase in matrix metalloproteinases 13 (MMP13) and a decrease in Aggrecan (ACAN)." (PMID 41013182, 2025). "Similarly, in our study, we observed increased MMP13 expression and decreased levels of aggrecan and collagen II, the main components of the extracellular matrix, indicating ongoing cartilage damage in MIA-induced osteoarthritis." (PMID 38045809, 2023). "Aggrecan, Col-10, MMP-13, SOX6, and Runx2 are closely related to osteoarthritis." (PMID 34926690, 2021). "Treating cartilage explants with trypsin has been shown to strip aggrecan from the explant without damaging chondrocytes, HA, or collagen, and serves as an ex vivo model for osteoarthritis." (PMID 34575579, 2021). "Lost ECM (the extracellular matrix) homeostasis is a central event in pathogenesis of osteoarthritis that results from increased expression and activity of proteolytic enzymes degrading ECM, and decreased expression of ECM proteins, such as aggrecan or collagen type 2." (PMID 34830409, 2021). "The changes in expression of the DEGs listed in the osteoarthritis pathway included strong down-regulation of cartilage matrix molecules (COL2A1, MATN3, and ACAN) and up-regulation of matrix proteases (ADAMTS5 and MMP13) and apoptosis-related molecules (CASP4)." (PMID 32294904, 2020). "Our data show that FJH-KO supplementation in rats with MIA induced osteoarthritis significantly increased the expression of aggrecan and collagens compared with that in rats not supplemented with FJH-KO." (PMID 33233504, 2020). "The pathogenesis of osteoarthritis is characterized by an imbalance between the degradation and synthesis of the cartilage ECM, with type II collagen and aggrecan being the primary components that play critical roles in the viscoelasticity and tensile strength of cartilage." (PMID 31608236, 2019). "Although the findings in human and other species indicate that the absence or reduction of the aggrecan in the cartilage ECM leads to chondrodysplasias and osteoarthritis, the correlation between the level of aggrecan expression and the clinical manifestation of the diseases is not clear." (PMID 30813547, 2019). "The findings suggested that introduction of miR-448 significantly decreased the protein expression of matrilin-3 and the mRNA levels of aggrecan and type II collagen, and enhanced the secreted protein expression of MMP-13 compared with osteoarthritis chondrocytes transfected with miR-NC." (PMID 29483929, 2018). "Little and colleagues reported catabolic aggrecan degradation in normal and osteoarthritis cartilage primarily involved cleavage by aggrecanase and not by MMPs." (PMID 22394620, 2012).
osteoarthritis (continued). "Therefore, pharmacological upregulation of XT-I gene expression along with aggrecan core protein might be expected to increase the amount of functional PG being synthesized and have a therapeutic potential for cartilage repair in OA and also in other degenerative joint diseases." (PMID 22479506, 2012). "Its overexpression induces suppression of SMAD3, resulting in inhibition of cell proliferation, migration, and invasion in osteosarcoma cells, and in downregulation of COL2A1 and Aggrecan and upregulation of ADAMTS in chondrocytes, which may be involved in the development of osteoarthritis." (PMID 35401675, 2022). "At present, the fOCD-linked missense variants, along with short stature and osteoarthritis-linked aggrecan variants have been classified together into one group (OMIM 165800, Short stature and advanced bone age, with or without early-onset osteoarthritis and/or osteochondritis dissecans)." (PMID 35338222, 2022). "The degradation of versican and aggrecan by ADAMTS (a disintegrin and metalloprotease with thrombospondin motifs) proteases is essential in ECM reorganization in both pathological and physiological processes, including osteoarthritis, atherosclerosis, and regulation of cardiac organogenesis." (PMID 24595230, 2014). "MMPs may also contribute to the aggrecan degradation as increased production of MMP-13, one of the major members of the MMP family responsible for pathological changes in degenerative joint diseases, has been recently reported in the synovial fluid from KBD patients." (PMID 22733148, 2012). "Indeed, ADAMTS8 expression in cartilage is not significantly altered in murine models of osteoarthritis as would be expected if ADAMTS8 is critically involved in aggrecan turnover." (PMID 34687701, 2021). "In line with our observations, the liberation of total or spliced ACAN following matrix breakdown during osteoarthritis progression has been described ACAN gene expression persisting throughout the experiment in CHDR and SFB did not correlate with an increased ACAN protein level." (PMID 24877141, 2014).
Arthritis (44 papers, 2005 to 2025). Inflammation of a joint. "As aggrecan is also present in the articular cartilage and intervertebral discs, early onset arthritis and intervertebral disc degenerative disease appears frequently in ACAN gene variants." (PMID 39749023, 2024). "Out of these four epitopes, three were found in the G1 and one in the G3 domain of PG aggrecan underlining the importance of these regions in the induction of arthritis." (PMID 24605340, 2014). "Although female BALB/c mice are close to 100% susceptible to PG-induced arthritis after three consecutive immunizations with human cartilage PG aggrecan, we found significant differences in arthritis severity, onset, and progression among the inbred colonies." (PMID 19220900, 2009). "Similarly, transgenic mice with a knock-in mutation of aggrecan preventing ‘aggrecanase’ cleavage of the Glu373 ~ Ala374 bond also develop less severe OA in the surgical OA and antigen-induced arthritis models." (PMID 32772139, 2021). "Loss of aggrecan is believed to be the main manifestation of early arthritis." (PMID 28426786, 2017). "The loss of PG aggrecan is a major feature of cartilage degradation associated with arthritis." (PMID 24605340, 2014). "Aggrecan is another core structural protein in the cartilage ECM that presents as the initial histological indication of cartilage deterioration in arthritis and fully demonstrates the importance of aggrecan degradation in cartilage tissue for OA." (PMID 38259516, 2023). "It is believed that aggrecan degradation is a phenomenon that occurs in the early stages of arthritis in children and is likely to precede irreversible changes in the weaving structure of collagen fibers." (PMID 33924892, 2021). "Recombinant human G1-induced arthritis is provoked by repeated intraperitoneal injections of the aggrecan G1 domain in the dimethyl-dioctadecyl-ammonium (DDA) adjuvant." (PMID 32859051, 2020). "We induced arthritis with immunization of recombinant human proteoglycan aggrecan G1 domain in Nkx2-3−/− and control BALB/c mice." (PMID 32859051, 2020). "The increased degradation of cartilage collagen and the proteoglycan aggrecan (ACAN) principally leads to the degeneration of articular cartilage in arthritic joint diseases." (PMID 32811552, 2020). "Aggrecan loss in articular cartilage is predominantly a proteolytic process mediated by MMP and ADAMTS proteases and has been extensively studied in arthritis." (PMID 31371388, 2019). "As reported, a baseline level of aggrecan turnover is mediated by MMPs, whereas ADAMTSs are known to initiate cartilage damage in arthritis." (PMID 31371388, 2019). "Thus, aggrecan likely prevents access of collagenolytic proteinases to collagen fibril in the tissue, and aggrecan loss may be a trigger for cartilage erosion during the development of arthritis." (PMID 28270508, 2017). "ADAMTS5 has become a major drug target for arthritis therapy as ADAMTS5 knockout mice (Adamts5-/- mice) are resistant to aggrecan cleavage in articular cartilage and are thus protected from experimentally induced arthritis." (PMID 27855162, 2016). "Aggrecan breakdown is reversible, but the irreversibility of collagen release makes its prevention key for developing effective therapies for arthritis." (PMID 24757149, 2014). "In this review, the role of various T cell epitopes of aggrecan in the induction of autoreactive T cell activation and arthritis is discussed." (PMID 24605340, 2014). "Since arthritis is characterized by irreversible loss of ECM, we also wanted to include collagen and aggrecan degradation in the model." (PMID 24757149, 2014). "The protein is well-characterized for its role in aggrecan cleavage and consequently its involvement in articular cartilage degradation in arthritis." (PMID 24213506, 2012). "When quantified by a western blot method, the proportion of aggrecan in SF having the neoepitope ARGS was elevated in arthritis and joint injury compared with individuals with healthy knees." (PMID 19545413, 2009).